HIF1A (hypoxia inducible factor 1 subunit alpha)
Diseases named in the same sentence as HIF1A in open-access papers (continued):
Sharing a sentence is not in itself a finding about the gene and the disease.
melanoma (continued). "Given the profound effect of HIF1a on NK cell‐dependent pulmonary metastasis in vivo, we decided to analyze abundance and phenotype of NK cells in lungs from mice after i.v. injection of B16 melanoma cells." (PMID 36987917, 2023). "In this study, we aim to identify an epigenetic regulator of HIF-1α that could be targeted for therapeutic interventions in melanoma." (PMID 36831463, 2023). "HIF-1α is expressed in mast cells of human and animal melanoma tissues." (PMID 36761171, 2022). "In a highly hypoxic and PD-1-resistant B16-F10 melanoma mouse model, we recently reported that inhibiting hypoxia by preventing HIF-1α/β heterodimerization in a mouse melanoma model drives immune cells into the tumor microenvironment and improves anti-PD-1- and vaccine-based immunotherapies." (PMID 35795658, 2022). "HIF-1α expression is related to aggressive characteristics of melanoma." (PMID 36224606, 2022). "To verify a role for HIF1 in the hypoxic mRNA regulation of PD-L1 expression in melanoma cells, we tested whether HIF1α knockdown would affect PD-L1 expression." (PMID 34268602, 2022). "Among melanoma subpopulations, varying levels of HIF1α expression were observed." (PMID 34268602, 2022). "Similarly, we found a significant positive association between HIF1α and SOX2 (R = 0.49, p-value = 0.0089) along with CD44 and SOX2 (R = 0.39, p-value = 0.045) in melanoma cancers." (PMID 35186918, 2022). "In addition, transfection with miR-199a-5p mimics reduced cell proliferation in melanoma cells by decreasing HIF-1α expression, demonstrating the therapeutic potential of this and other miRNAs in melanoma." (PMID 35804995, 2022). "In mouse neural progenitor cells GM-CSF treatment induces a PI3K–NF-κB signaling pathway that increases HIF-1α expression, and in a mouse melanoma model GM-CSF treatment induces macrophage secretion of vascular endothelial growth factor (VEGF) in a HIF-1α-dependent manner." (PMID 35877763, 2022). "In melanoma, IL22RA1 mutation upregulated the expression of genes involved in the hypoxia-inducible factor-1alpha (HIF-1α) signaling pathway, whereas the metabolic pathways including biosynthesis of unsaturated fatty acids and butanoate metabolism were downregulated." (PMID 35874683, 2022). "Finally, we used IHC to compare the expression of HIF-1α in the intraosseous and extraosseous regions of five melanoma tissues collected using curative intent surgery." (PMID 36669005, 2022). "Pivaloyloxymethyl butyrate (Pivanex, AN-9) is the other short-chain fatty acid that is in phase I/II clinical trials for malignant melanoma, and AN-9 exhibited antimetastatic and antiangiogenic activities via decreasing vascularization, bFGF expression, and HIF-1α." (PMID 36224606, 2022). "A study by Lequeux and coworkers investigated the inhibition of HIF-1α activity on cytotoxic immune cell infiltration into B16-F10 melanoma, and found an increase in infiltration of NK and CD8+ effector T cells and a significantly increased response to anti-PD-1 blockade." (PMID 35211123, 2022). "Since hypoxia-inducible factor-1α (HIF-1α) allows cell growth under metabolic stress and hypoxia, Egger’s team hypothesized that a combination of an HIF-1α inhibitor and chloroquine would have an anti-tumor effect on melanoma cells." (PMID 34360634, 2021). "And can inhibit the invasion ability of melanoma through NF-κB and HIF-1α signal pathway." (PMID 34239596, 2021). "In addition, hypoxia induces Akt hyperactivation, which cooperates with HIF1α to promote Notch1 expression, an effector that drives melanoma phenotype switching." (PMID 34604096, 2021). "Increased HIF-1α promoted by BRAFV600E could contribute to intensify and foster melanoma genesis in association to PI3K-Akt pathway, which is known to play a relevant role in early melanoma." (PMID 33964953, 2021). "Mechanistically, hypoxia drives melanoma phenotype switching in a HIF1α-dependent manner." (PMID 34604096, 2021).
melanoma (continued). "Indeed, PKM has been identified as one of the major hypoxia-induced HIF1α targets in melanocytes that significantly correlate with reduced melanoma disease-free status." (PMID 33937086, 2021). "PI3Kγ expression on B16F10 melanoma cells promotes metastasis to the lungs of mice suffering from melanoma caused via the injection of B16F10 cells to their tail veins through increasing the expression of MMP-9, uPA, VEGF, HIF-1α, and HIF-2α by tumor-associated macrophages (TAMs)." (PMID 32902664, 2021). "Moreover, melanoma xenografts obtained inoculating mouse melanoma cells into mouse ischemic limbs, showed an increase in vasculogenic mimicry under ischemic condition, and higher expression of HIF-1α, VEGF, matrix metalloproteinases 2 (MMP2), and MMP9." (PMID 33964953, 2021). "MiR-210, a direct target of HIF-1α, was found to be significantly higher in metastatic CM biopsies compared to primary ones, and circulating miR-210 in plasma allowed to identify early systemic metastasis recurrence in melanoma patients." (PMID 33964953, 2021). "Furthermore, treatments with baicalein and baicalin significantly inhibited HIF1α expression in all melanoma cells, suggesting down-regulation of HIF1α pathway in melanoma cells induced by the two compounds." (PMID 32984331, 2020). "Finally, we identified AGTRAP, a HIF1α direct target related to reduced PFS in melanoma and to tumor growth and angiogenesis in Lewis lung carcinoma." (PMID 32204550, 2020). "Additionally, we observed an up-regulation of HIF-1α protein in tumors of xenografted melanoma mice." (PMID 32793477, 2020). "However, many experimental evidence showed that HIF-1α and several of its target genes are strongly upregulated in melanoma cells not only during hypoxia, but also in normoxic conditions." (PMID 32528879, 2020). "The four melanoma cell lines expressed high levels of HIF1α." (PMID 32984331, 2020). "In particular, under hypoxia and normoxia, HIF-1α can increase the expression of urokinase plasminogen activator receptor (uPAR), which in turn leads to a glycolytic and invasive phenotype in melanoma cells in a EGFR-dependent manner with involvement of the PI3K/mTOR/HIF-1α pathway." (PMID 32528879, 2020). "Indeed, it was shown that Elongator promotes glycolysis in melanoma cells through the XAA codon-dependent increase of HIF1α translation, which ultimately results in strong resistance to targeted therapy." (PMID 34968241, 2020). "Interestingly, it is also known that mutant BRAF, a common event on CMS1 tumors, regulates HIF-1α expression in melanoma, affecting cell survival under hypoxic conditions." (PMID 32231135, 2020). "Hypoxia increases Cx43 expression in human melanoma cells via HIF-1α transcriptional activation." (PMID 33066331, 2020). "Interestingly, we previously reported that Cx43 expression is transcriptionally induced by HIF-1α in hypoxic melanoma cells." (PMID 33066331, 2020). "Thus, a previous report has suggested that the pro-angiogenic response of melanoma to low levels of oxygen depends at least in part on HIF-1α mediated downregulation of MITF." (PMID 33396270, 2020). "Since acriflavine treatment results in the consistent death of melanoma cells, our results suggest that inhibition of HIF-1α function in melanoma could open new avenues for the treatment of this deadly disease regardless of the hypoxic condition of the tumor." (PMID 33396270, 2020). "KIT mutant was reported to require HIF-1α to transform melanocytes into melanoma cells." (PMID 33133157, 2020). "Consequently, the upregulation and the protein stabilization of HIF-1α lead to the glycolysis induction in melanoma cells and to melanoma development and progression both in the presence and in the absence of oxygen." (PMID 32528879, 2020). "Here, we used acriflavine, a potent inhibitor of HIF-1α dimerization, as a tool to investigate whether HIF-1α-regulated pathways contribute to the growth of melanoma cells under normoxia." (PMID 33396270, 2020).
melanoma (continued). "In addition, HIF1-α knockdown contributed to enhancing TET2 expression in melanoma and glioblastoma cells, which shed new light on the plausible regulation of expression between these two proteins in malignant cells." (PMID 33352824, 2020). "For example, hypoxia could induce Cav-1 protein levels in a HIF1α-dependent manner in murine melanoma and colon-adenocarcinoma cells." (PMID 32528105, 2020). "In melanoma, HIF1α is well substantiated to promote tumorigenesis." (PMID 31371307, 2019). "Similarly, NOX5-derived ROS elevated the proliferation of human UACC-257 melanoma cells via stimulating HIF-1α expression, further enhancing new blood vessel formation and accelerating the growth and invasion of tumors." (PMID 31636809, 2019). "Therefore, we have revealed that the functions of miRNA-138 and HIF1α and their correlation are important for the clinical treatment of melanoma." (PMID 31371307, 2019). "Our data from the tumor tissues of melanoma patients from different stages show that the expression of miRNA-138 decreases progressively with the enhancement of metastatic potential and the corresponding HIF1α level increases gradually." (PMID 31371307, 2019). "The late stages of melanoma tissues had further decreased miRNA-138 and increased HIF1α expression." (PMID 31371307, 2019). "Therefore, our findings demonstrate that CXCR7 promotes HIF-1α translation in melanoma by facilitating Src-mediated eIF4E phosphorylation." (PMID 30804329, 2019). "HIF1α has been identified as the direct downstream target of miRNA-138 in melanoma." (PMID 31371307, 2019). "Several oxygen-independent pathways that regulate HIF-1α were identified in melanomas." (PMID 31781212, 2019). "There are several hypoxia-independent mechanisms that lead to the activation of HIF1a, however, as was reported in (cutaneous) melanoma for the phosphoinositide 3-kinsase (PI3K) signalling or presence of reactive oxygen species (ROS) and increased nuclear factor kappa-B (NF-κB) activity." (PMID 31323773, 2019). "Importantly, we found that luteolin inhibited melanoma cell migration, invasion, adhesion, and capillary tube formation abilities by inhibiting the HIF‐1α/VEGF signaling pathway." (PMID 30653763, 2019). "By quantitative real-time PCR analysis, it was shown that α-MSH significantly augmented HIF-1α mRNA expression in B16-F10 melanoma cells during hypoxia compared with the CoCl2 only group, although the mRNA level of HIF-1α was only slight increased in α-MSH-treated cells in normoxia." (PMID 30062060, 2018). "These HIF1α variations might be enough for the metabolic changes observed in our experimental models of SOX2-manipulated melanoma cells." (PMID 30466459, 2018). "Therefore, our study indicates that increased ROS production and oxidative stress induced by OSA-like IH promote melanoma lung metastasis, which is in part regulated through up-regulation of HIF-1α expression." (PMID 29433520, 2018). "Therefore, efforts to target melanoma angiogenesis suggested that the remaining cancer cells developed scavenger mechanisms, such as overexpression of HIF-1α, as a result of hypoxia and oxidative stress generated by these treatments." (PMID 30138430, 2018). "Given the results obtained after modulation of SOX2 expression in melanoma cell lines grown in acidic and standard conditions, we hypothesized the involvement of HIF1α transcription factor in SOX2-driven metabolic adaptation." (PMID 30466459, 2018). "Thus, the anti-oxidant action on the co-culture milieu was the principal cause for simultaneous suppression of key molecules involved in tumor progression in both cell types tested (reduction of HIF-1α levels in melanoma cells and ARG-1 levels in TAMs)." (PMID 30138430, 2018). "Therefore, the present study unveils that POMC therapy induces the activation of autophagic and apoptotic cell death pathways in melanoma cells through α-MSH/HIF-1α/BNIP3 signaling." (PMID 30062060, 2018).
melanoma (continued). "Vitamin C can reduce tumor growth, invasion and metastasis of melanoma in mice by inhibiting the hypoxia inducible factor-1 alpha (HIF-1α) transcriptional activity, which might play a key role in melanoma carcinogenesis." (PMID 30022952, 2018). "Thus, our recent studies proved that the antitumor activity of SIM on melanoma development was exerted via strong inhibitory effects on TAMs-mediated oxidative stress and intratumor production of HIF-1α." (PMID 30138430, 2018). "Therefore, the present study unveiled a unique function of autophagy in promoting cell death during POMC-mediated melanoma suppression via α-MSH/HIF-1α/BNIP3/BNIP3L signaling pathway." (PMID 30062060, 2018). "However, in our experimental setup migration was increased under hypoxic conditions in the well-motile melanoma cell line, and HIF-1α silencing blocked this effect." (PMID 28562340, 2017). "Melanogenesis could simulate HIF-1α expression, thereby conferring malignant behaviors of melanoma cells." (PMID 29244840, 2017). "It has been reported that miR-199a-5p may also target HIF-1α to reduce proliferation and angiogenesis in melanoma, multiple myeloma and soft tissue sarcoma." (PMID 29137361, 2017). "In our previous study, we confirmed that HIF-1α is a direct gene target of miR-33a in melanoma." (PMID 29137372, 2017). "miR-33a-5p plays an inhibitory role in glycolysis in melanoma, suggesting HIF-1α may involve in this activity." (PMID 29137372, 2017). "Interestingly, HIF-1α mRNA was significantly decreased by vanillin treatment in A2058 melanoma cells." (PMID 28257048, 2017). "In this study, we examined whether vanillin has anti-cancer and anti-metastatic activities via inhibition of hypoxia-inducible factor-1α (HIF-1α) in A2058 and A375 human malignant melanoma cells." (PMID 28257048, 2017). "Importantly, HT168-M1 human melanoma cells with high baseline migration capacity showed increased HIF-1α and small GTPases expression, RhoA activation and migration under hypoxia." (PMID 28562340, 2017). "HIF1α RNA expression was overall high in human melanoma and epidermoid carcinoma cell lines." (PMID 28806730, 2017). "HIF-1α transcript levels were not affected by ET-1 treatment in CLL cells (data not shown), suggesting that its accumulation may be due to an increased HIF-1α stability as previously reported in melanoma cells." (PMID 29163807, 2017). "To further confirm that HIF-1α could contribute to hnRNP A18 growth promoting activity, we down regulated HIF-1α in melanoma cells and measured cell viability in the presence of CoCl2." (PMID 26824423, 2016). "HIF-1α is a direct target in melanoma, where miR-33a has a lower expression and could promote cell proliferation, invasion, and metastasis." (PMID 27551267, 2016). "To determine whether hnRNP A18 could affect HIF-1α functions in growing tumors in vivo we evaluated the angiogenic proteomes of melanoma tumors expressing endogenous or reduced hnRNP A18 levels." (PMID 26824423, 2016). "Additionally, reducing HIF-1α levels with A2P resulted in a significant reduction in the ability of the melanoma cells to invade through Matrigel." (PMID 26547841, 2015). "Next we investigated the hypothesis that the effect of AA on decreasing HIF-1α in human melanoma cells was mediated through stimulation of PHD and or FIH activity." (PMID 26547841, 2015). "Hypoxia inducible factor-1 alpha (HIF-1α) is thought to play a role in melanoma carcinogenesis." (PMID 26547841, 2015). "The overexpression of intra-tumor HIF-1α, as well as ascorbic acid deficiency has been noted not only in melanoma, but in other tumor types as well." (PMID 26547841, 2015). "A melanoma xenograft model was used to detect HIF1α and CAIX expression in vivo." (PMID 25997619, 2015). "Clinical samples of human melanoma express high levels of HIF-1α." (PMID 26547841, 2015). "Our studies suggest a positive role for ascorbic acid in regulating HIF-1α in melanoma." (PMID 26547841, 2015).
melanoma (continued). "However, when N-acetyl cysteine, a ROS scavenger, was added to the system, HIF1-α accumulation and melanoma cell invasion were inhibited." (PMID 23937926, 2013). "In agreement with the data of a previous report, HIF-1α was expressed in primary melanoma tissues." (PMID 23043612, 2012). "HIF-1α was increased in both nuclear and cytoplasmic extracts of Elesclomol-treated melanoma cells." (PMID 22912665, 2012). "To verify that the effect exerted by media from mutated fibroblasts on the invasiveness of melanoma cells are effectively due to their ROS production and HIF-1α stabilization, we analyzed HIF-1α level and melanoma cell invasion in the presence of NAC (N-acetyl cysteine), a ROS scavenger." (PMID 22272371, 2012). "Interestingly, knock-down of HIF1α in SBcl2 melanoma cells diminished VEGF and BNIP3 mRNA induction by hypoxia, although to a lesser extent than observed in melanocytes." (PMID 22457728, 2012). "On the other hand, patients with high serum LDH bear melanomas with hypoxic areas that produce high HIF-1α levels which upregulate components of the glycolytic pathway in addition to components of the angiogenesis pathway, such as the vascular endothelial growth factor." (PMID 23043612, 2012). "To further explore whether HIF was involved in the decrease in PEDF protein levels imposed by hypoxia in primary melanocytes (M13) and SBcl2 melanoma cells, we silenced HIF1α expression using shRNAmir to HIF1α (shHIF1α delivered by lentiviral transduction." (PMID 22457728, 2012). "Moreover, ET-1 and ET-3 promote invasive behaviour via hypoxia inducible factor 1 alpha (HIF-1α) in human melanoma cells." (PMID 24281035, 2010). "Since HIF-1α protein was increased in human melanoma cells under normoxic conditions, we determined whether this increase might be due to increased HIF-1α mRNA levels." (PMID 19919690, 2009). "However, there are few investigations into the normoxic expression of HIF-1α in human melanoma and its role in the malignant progression of this disease." (PMID 19919690, 2009). "The expanded role of HIF-1α in melanoma biology increases its importance as a therapeutic target." (PMID 19919690, 2009). "Therefore, one possibility is that the increase in HIF-1α that we observed in melanoma ceils is due to the hypoxic adoptive response maintained by the cells in culture." (PMID 19919690, 2009). "Activation of this pathway is correlated with the upregulation of HIF-1α mRNA in human melanoma." (PMID 19919690, 2009). "In contrast, staining with HIF-1α antibody showed little effect in melanoma cells." (PMID 15341671, 2004). "Similarly, the A3AR antagonist blocked HIF‐1α protein accumulation in A375 melanoma cells." (PMID 40181576, 2025). "Furthermore, studies have found that CTU2 is highly expressed in BRAFV600E-expressing melanoma cells, potentially promoting glycolysis by codon-biased regulation of HIF1α mRNA translation, which is rich in U34 codons, and maintaining high levels of HIF1α protein." (PMID 40375999, 2025). "Therefore, HDAC8-selective inhibitors may function as indirect HIF-1α inhibitors and may be a promising strategy in treating patients with melanoma." (PMID 36831463, 2023). "Hif1a encodes for a highly active transcription factor in melanoma, and we could not see statistical differences in Hif1a expression levels among the treatments." (PMID 36672229, 2023). "In experimental conditions similar to ours, using different BRAFV600E-mutated melanoma cells, other authors showed that in some cell lines cultured under hypoxia HIF-1α expression was reduced in response to PLX4032 but not in others, even though pERK resulted always reduced." (PMID 35740068, 2022). "Hence, the incorporation of HIF-1α as a promising prognostic indicator in melanoma may add growing value to current staging procedures." (PMID 36224606, 2022).